LEP (leptin)
Diseases named in the same sentence as LEP in open-access papers (continued):
Sharing a sentence is not in itself a finding about the gene and the disease.
diabetes (continued). "For instance, db/db mice and Zucker Diabetic Fatty (ZDF) rats develop symptoms similar to human diabetes due to a mutation in the Lepr gene, which encodes the receptor for a “satiety hormone”, leptin." (PMID 28678787, 2017). "Whilst women with depressive symptoms had significantly higher risk factors associated with diabetes (central obesity levels, IR, leptin and TNF-α), depression in men was associated with higher levels of CRP which potentially suggests an increased risk of CVD." (PMID 29190710, 2017). "To test this, we investigated mouse models with monogenic defects in leptin signaling which are susceptible to adipositas (C57BL/6 Cg-Lepob (obob)) or adipositas with diabetes (C57BL/KS Cg-Leprdb (dbdb)) according to their genetic background." (PMID 28885548, 2017). "In this study, we treated leptin-deficient ob/ob mice with organo-chalcogen Zn complexes, and evaluated the resulting anti-diabetic effects in a mouse model of diabetes arising from pathogenic mechanisms different from those in KKAy mice." (PMID 29215553, 2017). "Our findings are also compatible with those linking odd-chain saturated fatty acids to cardiovascular disease and diabetes, the risks of which have been associated with leptin and PAI-1." (PMID 28552966, 2017). "Leptin‐deficient ob/ob mice have diabetes and are obese, and they also exhibit hyperinsulinemia and hyperglycemia levels." (PMID 27357657, 2016). "Streptozotocin (STZ)-induced diabetes is an extensively used mouse model for type 1 diabetes, whereas leptin or leptin receptor (Lepr)-deficient mice, ob/ob and db/db respectively, are frequently used as models of type 2 diabetes." (PMID 27188595, 2016). "Polypeptide hormones (Leptin) can increase the disease risk of diabetes and breast cancer to some extent, and they have acceleration functions to the generation of diabetes and breast cancer." (PMID 27333326, 2016). "Expression of transcription factors (ANGPTL2, HP, LEP, SAA1, SAA2), genes related to inflammation (SAA1, LEP), diabetes (IGFBP5) and cancer risk (SAA2) were also elevated upon exposure to 5 nM PhIP.." (PMID 27547236, 2016). "Leptin can facilitate glucose utilization and improve insulin sensitivity, which has been implicated in the development of diabetes." (PMID 27195302, 2016). "Leptin-deficient ob/ob mice are overweight, insulin-resistant, and develop type 2 diabetes mellitus over time due to deficiency of the appetite regulating hormone leptin, which has immunomodulatory properties." (PMID 27486384, 2016). "For instance, antipsychotics such as clozapine and olanzapine have adipogenic potential, especially in influencing adiponectin and leptin levels, and carry the risk for the development of hypertension, diabetes and lipid abnormalities." (PMID 27941599, 2016). "Altogether, to our knowledge, no study has ever assessed the associations between birth weight, diabetes and fat mass, and leptin or adiponectin levels in middle age people." (PMID 27141948, 2016). "Diabetes and obesity are states of chronic inflammation associated with elevated levels of leptin and low levels of adiponectin." (PMID 26441826, 2015). "High circulating leptin levels have earlier been reported to be associated with diabetes incidence and also with development of other components of the metabolic syndrome." (PMID 25994184, 2015). "Odds ratio of CKD associated with elevated adiponectin and leptin levels were estimated using logistic regression models adjusted for age, gender, ethnicity, education, smoking, body mass index, diabetes, blood pressure, total and HDL cholesterol." (PMID 25793395, 2015). "These associations persisted when leptin and adiponectin were analyzed as continuous variables and remained consistent within subgroups of gender, ethnicity, overweight, diabetes and hypertension status." (PMID 25793395, 2015).
diabetes (continued). "Diabetes was identified in ob/ob mice in the late 1940s and later linked to a single autosomal recessive mutation on the obese gene (leptin encoding gene on chromosome 6, Lepob)." (PMID 24809394, 2014). "Due to the multifaceted role of leptin, spontaneous mutations have led to leptin signaling abnormalities, which were among the earliest factors discovered to cause diabetes-like symptoms in rodents." (PMID 24809394, 2014). "Serum albumin, γ-GTP, leptin, resistin, and hyaluronic acid, as well as the presence of diabetes, were associated with hepatic steatosis (≥5%) in the univariate analysis." (PMID 24524410, 2014). "In previous analyses, we have shown that leptin is a major risk factor for diabetes in minimally adjusted models, yet appears as a protective factor after adjustment for adiposity, inflammation markers and insulin." (PMID 23806173, 2013). "Here, we appear to be witnessing a similar phenomenon - the addition of leptin to our adiposity-diabetes analyses reveals a concomitant risk due to leptin resistance." (PMID 23806173, 2013). "Increased leptin levels following insulin treatment in rodents and in diabetic patients suggest the insulin deficiency as the cause of altered leptin levels in diabetes." (PMID 23853613, 2013). "The impact of age, waist circumference and leptin is in line with other investigations on risk for diabetes." (PMID 24098730, 2013). "The decrease of body fat stores in uncontrolled insulin-deficient diabetes results in marked reduce of plasma leptin levels." (PMID 23579596, 2013). "One study examining the impact of combined Htr2c null and ob/ob leptin null mutations revealed a synergistic effect on glucose regulation, indicated by a marked exacerbation of the diabetes phenotype characteristic of the ob/ob genotype." (PMID 23543912, 2013). "Leptin exerts its biological actions through the activation of its cognate receptors, which are encoded by the diabetes gene (db) and belong to the class I cytokine receptor superfamily." (PMID 22910888, 2012). "Even after adjusted for compounding factors like TNF-α, IL-6, and leptin, adiponectin stood as independent marker of association with genetic predisposition for future development of diabetes (P < 0.01)." (PMID 23213322, 2012). "Further studies, which reveal nuclear receptor binding to specific response elements present in Slco promoters, will further elucidate how these transporters are regulated in leptin/leptin receptor deficient diabetes models." (PMID 22524730, 2012). "Both CRP and leptin levels were independently associated with several cardiovascular risk factors, including diabetes, hypercholesterolemia and metabolic syndrome in both men and women (P < 0.05)." (PMID 22533665, 2012). "A lack of substrates like glucose in the cellular energy stores as shown in newly manifested type 1 diabetes mellitus (T1DM) or anorexia nervosa is associated with an up to a 100-fold molar excess of sOb-R over leptin in blood." (PMID 22545089, 2012). "In both men and women, diabetes, hypercholesterolemia and metabolic syndrome were significantly associated with elevated leptin levels." (PMID 22533665, 2012). "Leptin exerts its biological actions through the activation of its OB-Rb long-form receptor isoform which is encoded by the gene diabetes (db) and belongs to the class 1 cytokine receptor superfamily." (PMID 22046513, 2011). "Measurements comprised total and HMW adiponectin, leptin, as well as a panel of proinflammatory adipokines/chemokines associated with diabetes risk." (PMID 21365005, 2011). "This early incidence or progression of diabetes is considered to be caused by hyperphagia, which is associated with a leptin signal abnormality induced by introduction of the fa allele." (PMID 19696902, 2009).
diabetes (continued). "Given heterogeneity across studies, single adipokines have limited stand‐alone predictive value; the adiponectin–leptin ratio and inclusion within multimarker cardiometabolic panels may yield greater translational utility for risk prediction in diabetes." (PMID 41567175, 2026). "This assertion is based on the finding that in rodents with uncontrolled insulin-deficient diabetes, leptin action localized to the PBN is sufficient to normalize both glucagon levels and ketogenesis, presumably via projections to the VMN, despite having little effect on hyperglycemia." (PMID 40759579, 2025). "In a previous work of our group, a higher level of leptin was observed in individuals with youth-onset diabetes in Bangladesh, reflecting a leptin resistance that may be related to LEPR polymorphism." (PMID 40551902, 2025). "We investigated the association between body mass index (BMI), total body fat (TBF) and chronic kidney disease (CKD) and whether hypertension, diabetes, leptin and adiponectin mediated these associations." (PMID 38627329, 2024). "It has also been shown that increased levels of serum leptin could be used as a risk factor in the development of type 2 diabetes mellitus." (PMID 38792501, 2024). "Given that vascular risk factors—hypertension, diabetes, and hypercholesterolemia in particular—have been associated not only with Aβ or tau deposition, but also with leptin, they could potentially confound associations between plasma leptin and AD pathology." (PMID 38700863, 2024). "It remains unclear to what extent both hemodynamic (hypertension and diabetes) and hormonal (leptin and adiponectin) effects mediate the association between body fat and CKD." (PMID 38627329, 2024). "Furthermore, leptin SR level is linked to HbA1c value and TG level so it can be used in monitoring the response to treatment in patients with diabetes." (PMID 36950695, 2023). "A large prospective study indicated the association of high serum leptin concentrations with high risk of diabetes, and showed that serum leptin concentrations could predict incident diabetes." (PMID 36909317, 2023). "Hence, many studies found an association between the presence of serum leptin in newborns of mothers with diabetes and feeding difficulties." (PMID 37900684, 2023). "Leptin can cause vascular smooth muscle hypertrophy and oxidative stress, and stimulates vascular inflammation which may then lead to the development of type 2 diabetes mellitus, hypertension, atherosclerosis, and CAD." (PMID 36984571, 2023). "Both interventions were found to be equally good at a weight and showed improvement in risk markers of CVDs, cancer, and diabetes for example reduction in leptin, leptin to adiponectin ratio, inflammatory markers, fasting insulin, insulin resistance, blood pressure, and lipids." (PMID 35866077, 2022). "Diabetes during pregnancy is associated with elevated maternal insulin, leptin and IL-6." (PMID 35197933, 2022). "The severity of the induced diabetes in monogenic rodent models—such as leptin-deficient ob/ob and leptin receptor-deficient db/db mouse models, KK-Ay mice, and Otzhka Long-Evans Tokushima Fatty (OLETF) rats—is strongly affected by the strain’s genetic background." (PMID 36232867, 2022). "In the presence of maternal obesity and diabetes, increased birth weight could be a consequence of the trophic effects of hormones, including insulin and leptin, as well as a manifestation of either genetic predisposition or enhanced nutrient availability." (PMID 35197933, 2022). "Due to this, adiponectin appears to be more closely related to the risk of diabetes than leptin." (PMID 35712241, 2022). "Recently, we have reported that genetically diabetes-prone New Zealand Obese (NZO) mice, an obese mouse-strain used as model for polygenic diabetes, exhibit more adipocytes in the pancreas than diabetes-resistant, leptin-deficient B6.V-Lep ob/ob (B6-ob/ob) mice." (PMID 35216219, 2022).
diabetes (continued). "Notably, for plasma, stable analytes included the cytokines IL-1Ra and IL-2, and diabetes-associated proteins, such as C-Peptide, ghrelin and leptin." (PMID 33753773, 2021). "Leptin is associated with metabolism, insulin sensitivity, and diabetes." (PMID 34446063, 2021). "Worthy to note, diabetes mellitus (ß −6.773, p = 0.010) and residual renal function (coded as “no/yes”, ß 3.626, p = 0.039), but not dialysis vintage or delayed graft function, were associated with leptin change after renal transplantation." (PMID 34441040, 2021). "Leptin and interleukin-6 (IL-6) have proatherogenic effects, contributing to the development of classic risk factors for atherosclerosis including, arterial hypertension, diabetes mellitus (DM), endothelial dysfunction, inflammation and platelet activation." (PMID 33735200, 2021). "In conclusion, hepatic fibrosis progresses rapidly in NAFLD patients with not only hypopituitarism but also hypothalamus dysfunction, and this might be associated with BMI, diabetes mellitus, and leptin." (PMID 33102399, 2020). "Moreover, while global knockout of Scd1 in mice improves insulin sensitivity, when introduced on the ob/ob background with leptin-deficiency, Scd1 deletion leads to a worsening of diabetes." (PMID 31796987, 2020). "As albuminuria, leptin/adiponectin ratio and glycaemic control have been associated with progression of vascular complications of diabetes, our results prove that interval walking training is effective for improvement of vascular health in diabetes." (PMID 32652863, 2020). "To determine whether the reduced food intake shown by Pdk2-deficient mice following diabetes is due to changes in systemic insulin or leptin levels, we collected plasma from WT and Pdk2 KO mice at 3 weeks post-STZ injection." (PMID 33219201, 2020). "In the simple linear regression analysis, most variables (leptin, age, waist circumference, hypertension, and diabetes) were negatively associated with variation in T levels (p < 0.05), whereas E2 was only positively associated with T levels (R2 = 0.13, p = 0.0011)." (PMID 33179018, 2020). "Finally, we provide an outlook on recent perspectives on deciphering the underlying pathophysiological mechanisms of leptin-mediated cardiomyopathy and future therapeutic approaches for the treatment of diabetes-mediated cardiovascular disease." (PMID 32655492, 2020). "Gastritis caused by H. pylori may affect the secretion of gastric-related hormones, such as leptin and growth hormone-releasing hormone, as well as gastrin and somatostatin, which may affect the susceptibility to diabetes." (PMID 31583248, 2019). "Many clinical reports suggest that leptin might play a key link between metabolism and inflammation, across different age categories, ranging from pediatric to geriatric patients with diabetes or other cardiovascular risk factors." (PMID 30674322, 2019). "In 2015, Mendelian randomization-based analysis on nearly 500 mother–infant dyads (excluding women treated with insulin or treated for diabetes) showed that cord blood methylation near the LEP gene was associated with fasting plasma glucose (FPG) levels in pregnant woman." (PMID 31408957, 2019). "Due to leptin deficiency these mice develop metabolic syndrome/diabetes and hepatic steatosis." (PMID 30732594, 2019). "Previous studies have verified that serum leptin concentrations are associated with various diseases in dogs, including cardiovascular disease, pancreatitis, and hormone imbalances, such as hyperadrenocorticism, hypothyroidism, and diabetes mellitus." (PMID 31238989, 2019). "When these ATG7 KO mice were crossed to ob/ob mice (a model for obesity with a mutation in the leptin gene) the progeny displayed severe diabetes suggesting that autophagic impairment in obese animals might make them more susceptible to diabetes." (PMID 29950970, 2018).
diabetes (continued). "For SLE, it has been developed the Predictors of Risk for Elevated Flares, Damage Progression, and Increased Cardiovascular Disease in SLE (PREDICTS) model, which includes four inflammatory biomarkers (homocysteine, piHDL, TWEAK, and leptin) and two risk factors (age and diabetes)." (PMID 29435447, 2017). "Pregnant women who developed GDM had significantly (p<0.01) raisedfasting blood glucose, (p<0.014), BMI (P = 0.022),leptin, progesterone, estradiol (p<0.0001) than the pregnant women with low risk of diabetes but significantly low(p<0.0001) human placenta lactogen levels." (PMID 28732072, 2017). "However, the precise mechanisms by which leptin controls cardiovascular function in insulin-deficient diabetes and how leptin is capable of completely normalizing glucose levels even in the absence of adequate insulin production are still unclear." (PMID 29190687, 2017). "Some studies showed that there is a direct association between leptin and diabetes development." (PMID 28127544, 2017). "Diabetes is associated with decreased levels of adiponectin and increased levels of leptin." (PMID 28078101, 2017). "There is a controversy regarding the association between leptin levels & diabetes." (PMID 28127544, 2017). "This reflects a state of adiponectin deficiency and leptin resistance, which could be a possible mechanism for development of diabetes complications." (PMID 28078101, 2017). "Multivariable Cox proportional hazards modeling was performed to examine the association between leptin levels with incident cancer after adjusting for age, sex, race, smoking status, alcohol use, family history of malignancy, body mass index (BMI), diabetes mellitus and C-reactive protein." (PMID 27636369, 2016). "Specifically, studies examining the possible utility of combined insulin and leptin treatment for control of both hyperglycemia and hyperglucagonemia in insulin-deficient diabetes may be of particular value." (PMID 28702245, 2016). "This state of adiponectin deficiency and leptin resistance could be a possible mechanism for development of diabetes and its complications." (PMID 27200209, 2016). "Leptin is secreted principally by the adipocytes of the white adipose tissue and can curb the appetite and reduce the formulation and accumulation of fat, both of which are closely associated with the occurrence of type 2 diabetes mellitus." (PMID 27867820, 2016). "However, we did find that PhIP induces changes in gene expression in various genes that are related to inflammation (SAA1, LEP), diabetes (IBP5) and cancer risk (SAA2)." (PMID 27547236, 2016). "A higher association of HDL, TG, Leptin & Renin was seen with having FH of diabetes in our study." (PMID 26430439, 2015). "In addition, loss of glutamatergic input via GluN2B-containing NMDARs expressed on AgRP neurons entirely prevents development of diabetes in obese leptin-deficient animals." (PMID 26500840, 2015). "Based on multivariate regression analysis that included albumin (≥4.0 g/dl), γ-GTP (≥44 IU/L), leptin (≥8.6 ng/ml), resistin (≥8.8 ng/ml), hyaluronic acid (≥76.4 ng/ml), presence of diabetes, and age (≥55 years), leptin was independently associated with hepatic steatosis." (PMID 24524410, 2014). "From these results, the decreased level of plasma leptin and adiponectin levels in insulin-dependent diabetes mellitus may well be caused by an insulin deficiency and/or increased lipolysis." (PMID 24719626, 2013). "In addition, a strong inverse correlation between plasma sOb-R levels and the risk of developing type 2 diabetes mellitus in human patients points to an important role of sOb-R as modulator of leptin action." (PMID 22545089, 2012). "In mouse as well, whether single loss-of-function mutation in either leptin or its receptor develops severe diabetes depends on the genetic background." (PMID 23304119, 2012).